CRP (C-reactive protein)
Diseases named in the same sentence as CRP in open-access papers (continued):
Sharing a sentence is not in itself a finding about the gene and the disease.
diabetes (continued). "Furthermore, higher levels of inflammatory biomarkers CRP, IL‐6, and TNF‐α were reported to be associated with increased glycated hemoglobin (HbA1c) as a marker for type 2 diabetes mellitus." (PMID 33680494, 2021). "Models that included additional health and lifestyle covariates (BMI, smoking, alcohol consumption, hypertension, diabetes, and cardiovascular disease history) attenuated the relationship between DNAm CRP and brain health outcomes by up to 40% (eTable 5, links.lww.com/WNL/B629)." (PMID 34789543, 2021). "Univariate Cox proportional hazard analysis regarding prediction of cardiac death revealed that SAS score, presence of progressive AS, history of diabetes, history of ischemic heart disease, and serum levels of albumin and C-reactive protein were significant independent variables." (PMID 34513029, 2021). "Besides, we have found that age ≥70 years, diabetes, NYHA grade III, LVEF ≤55%, and CRP ≥10 mg/L are the independent risk factors of pulmonary infections in patients with heart failure." (PMID 34559121, 2021). "Compared to the participants with normal glucose tolerance (NGT), those with prediabetes or diabetes were, on average, older, they had a higher waist circumference, BMI, blood pressure, triglycerides, ultra-sensitive C-reactive protein (us-CRP), LDL-cholesterol and GGT, all p < 0.001." (PMID 34073154, 2021). "Another publication also reported a relationship between moderate to severe periodontitis and high cardiovascular risk (CRP > 3 mg/L), but it was lost after adjustment for CVD risk factors (sex, age, educational level, smoking, BMI, diabetes, and HDL cholesterol)." (PMID 34439905, 2021). "Similarly, in the general Japanese population elevated hs-CRP concentrations was a significant predictor of diabetes." (PMID 34138882, 2021). "In agreement with our results, RDW was found to be strongly correlated with high CRP levels in various populations: unselected subjects from the community, diabetics and populations with various degrees of renal impairment such as -Peritoneal Dialysis (PD), HD and CKD." (PMID 33266382, 2020). "In our study, kidney MSTN expression was neither related to the diabetes duration nor to HbA1c, while it was directly associated with serum C-reactive protein (CRP) levels." (PMID 32286342, 2020). "Participators were classified according to serum ferritin, diabetes, and two hs-CRP levels." (PMID 32280714, 2020). "Obese patients, patients >50 years old, andthose with elevated ESR and CRP had a higher incidence of lung infiltrates.Patients with comorbidities such as Diabetes Mellitus and hypertension had ahigher incidence of abnormal chest radiograph but without statisticalsignificance (p = 0.053)." (PMID 32742648, 2020). "Plasma levels of branched amino acids were positively associated with BMI, waist circumference, HOMA-IR, TG and C-reactive protein (0.19 < r < 0.25; n = 153; p < 0.05) in subjects without diabetes." (PMID 32292494, 2020). "One limitation of this study is that the total number of subjects was small, as we excluded patients with systemic diseases that might affect CRP levels such as cardiovascular disease, diabetes, arthritis, and uncontrolled systemic disease." (PMID 33424972, 2020). "Independent studies have implicated AMBP24, ApoA4, CRP, AHSG38 and HPX23 in DIO and diabetes." (PMID 32709962, 2020). "In another study, taking zinc supplement (30 mg per day of zinc sulphate) during 6 months did not cause any significant change in CRP in women with pre-diabetes." (PMID 32466773, 2020). "and elevation of the preprocedural CRP level in patients undergoing PCI was shown to be associated with the incidence of adverse cardiac events, such as: in-stent restenosis, especially for whose with obesity and diabetes." (PMID 32046736, 2020). "Monocyte hyperactivity may be reversed in patients with diabetes mellitus by scaling and root planing resulting in reduced monocyte-derived TNFα, high sensitive CRP and sE-selectin." (PMID 32486269, 2020).
diabetes (continued). "CRP levels were elevated in those who were obese (p < 0.0001) or who had diabetes (p < 0.03)." (PMID 32625121, 2020). "The apoB/apoA-I ratio remained significantly related to cancer mortality (HR: 1.17; 95% CI 1.09–1.25), even after adjusting for traditional risk factors (age, sex, race, alcohol and dietary intake, smoking, BMI, dyslipidemia, hypertension, and diabetes) and CRP." (PMID 31936330, 2020). "Among participants without diabetes, higher CRP concentration was associated with higher odds of PAD (1.10; 1.01 to 1.21, p=0.029) and nephropathy (1.12; 1.04 to 1.22, p=0.004)." (PMID 32665312, 2020). "It has been suggested that the H. pylori may be contributed to the incidence of cardiovascular disease and diabetes through elevations in inflammatory cytokines levels such as C-reactive protein (CRP) and interleukin-6." (PMID 32209055, 2020). "Another clinical significance of our results is the potential of using CRP as a marker for assessing or monitoring the risk of developing vascular dysfunction in individuals with and without diabetes." (PMID 32665312, 2020). "These associations were independent of age, gender, UACR, diabetes and CRP, body mass index, waist-hip ratio (WHR), cholesterol and triglycerides for serum bilirubin, albumin, and haemoglobin but not for concentration of ALT." (PMID 33261565, 2020). "We examined the association between CRP and diabetes and associated microvascular and macrovascular dysfunction in sub-Saharan Africans with and without diabetes." (PMID 32665312, 2020). "In exploring clinical factors that may explain the discordance between FFR and iFR, we found that gender, diabetes mellitus, hs-CRP level, aortic stenosis, and renal function were independently associated with iFR but not with FFR." (PMID 32760123, 2020). "Inverse univariate associations were found for age, BMI, smoking, cotinine excretion, SBP, DBP, coffee consumption, hs-CRP, GlycA, diabetes, glucose, total cholesterol:HDL cholesterol ratio, cystatin C, albumin excretion, and use of antihypertensives, antidiabetics, and statins (all P < 0.05)." (PMID 32899820, 2020). "Altered CRP levels in serum have been found to be associated with not only bipolar disorder, but also hypertension, stroke, coronary heart disease, type 2 diabetes mellitus, and cancer." (PMID 32066700, 2020). "Studies that reported lower risk of mortality for South Asians suggested age and sex, proteinuria, blood pressure, diabetes, cardiovascular disease and medications (antihypertensive drugs and statins), and C-reactive protein partly explained ethnic differences in mortality." (PMID 32517714, 2020). "After adjustment for age, gender, urine albumin/creatinine ratio, diabetes, BMI, CRP, WHR, alcohol consumption, cholesterol and triglycerides, low serum albumin (p < 0.001), haemoglobin (p = 0.012) and bilirubin (p = 0.011) were associated with annual decline in eGFR." (PMID 33261565, 2020). "Interleukin-6 was correlated with C-reactive protein (p < 0.0001) and with the incidence of insulin-dependent diabetes mellitus (p = 0.036), arterial hypertension (p = 0.044), reduced left ventricular function (p = 0.003), and severe coronary calcification (p = 0.015)." (PMID 32685095, 2020). "In participants without diabetes, higher CRP Z-score concentration was associated with higher odds of PAD and nephropathy." (PMID 32665312, 2020). "TNF-α and C-reactive protein levels are higher in patients with chronic pancreatitis and type 2 diabetes mellitus than those with isolated chronic pancreatitis, characterizing the persistence of chronic systemic inflammation in case of the combined clinical course of these diseases." (PMID 33456608, 2020). "CP patients with type 2 diabetes mellitus had the highest CRP indices (5.5-fold, p <0.05." (PMID 33456608, 2020).
diabetes (continued). "Increasing values of age, D-dimer, C-reactive protein, sequential organ failure assessment (SOFA) score and body temperature while decreasing albumin, and a history of diabetes were the risk factors with the highest consistency as predictors for covid-19 severity." (PMID 32491116, 2020). "Using peritonitis as the dependent variable, the following variables were included as covariates, to establish a binary logistic regression model: age, gender, diabetes mellitus, hemoglobin, albumin, serum creatinine, cholesterol, potassium, c-reactive protein (CRP), and season." (PMID 32781861, 2020). "Adding biomarkers into the model also had some explanatory power, particularly in men, mostly due to the high prevalence of diabetes and elevated HbA1c in the Asian population, and the presence of low grade inflammation as evidenced by higher C-reactive protein levels." (PMID 32497776, 2020). "The effects of the KL-VS polymorphism on MA was evaluated by multiple linear regression analysis including significant variables: sex, inflammatory status of patients (as serum CRP concentration), duration of diabetes, uric acid concentration, and KLOTHO genotype." (PMID 32435919, 2020). "In addition, the percentages of the highest quartile of CRP, smoking, hypertension, diabetes, and KSD were found to be higher in the increased arterial stiffness group." (PMID 32498283, 2020). "This association was observed independent of age, sex, BMI, h-CRP, smoking habits, alcohol consumption, physical activity, snoring, education, diabetes mellitus, and hypertension." (PMID 32799877, 2020). "At baseline, a substantial proportion of participants showed signs of insulin resistance (mean HOMA-IR 5.5 ± 3.4) despite not meeting the diagnostic criteria for diabetes, and low-level inflammation (mean CRP 3.9 mg/l ± 3.8 mg/l)." (PMID 32154197, 2020). "The median disease duration in the diabetes group was five years at inclusion and ten years at follow-up, and at inclusion, they had significantly higher levels of C-reactive protein (CRP), HbA1c, and anthropometric measures as well as total and low-density lipoprotein (LDL) cholesterol." (PMID 32309448, 2020). "There are several studies that supported a positive association between hs-CRP and kidney disease among patients with diabetes and nondiabetes despite remaining controversial." (PMID 32587865, 2020). "Participants with dyslipidemia were more likely to be men, have less than a high school education, be current smokers, be current drinkers, have a higher h-CRP level, have a higher blood pressure, have a higher prevalence of snoring symptoms, be overweight and have diabetes." (PMID 32799877, 2020). "However, diabetes patients showed higher neutrophil counts, higher CRP, IgE, and IL-6, TNF and IFN-γ levels." (PMID 33584667, 2020). "The presence of advanced age, active smoking, comorbidity, especially hypertension, diabetes, arrhythmia, coronary artery disease, congestive heart failure and neutrophil, C-reactive protein, lactate dehydrogenase, D-dimer and aspartate transaminase were associated with mortality." (PMID 34485485, 2020). "We also included proteinuria as well as elevated tacrolimus levels, CRP values, arterial hypertension and diabetes mellitus as factors that may influence thyroid hormones and eGFR in our analysis." (PMID 32034263, 2020). "Diabetes mellitus is a multifactorial metabolic disease and growing evidence shows that it is characterized by a state of sub-clinical inflammation, as reflected by chronic high levels of hs-CRP." (PMID 33081810, 2020). "Despite being of younger age, compared to White participants, Black and Asian individuals experienced a higher prevalence of diabetes, higher levels of HbA1c and C-reactive protein and lower forced expiratory volume Blacks also had higher BMI and Asians higher waist to hip ratio." (PMID 32497776, 2020).
diabetes (continued). "Higher TSAT levels were associated with male gender, age, the absence of diabetes, low levels of high-sensitivity CRP, and low β2 microglobulin levels, but not with intravenous iron administration or ferritin levels." (PMID 32877424, 2020). "Our study shows that in sub-Saharan Africans without diabetes, higher CRP concentration is significantly associated with PAD and nephropathy." (PMID 32665312, 2020). "Patients in the low ABI group had higher prevalence of diabetes mellitus (p = .044) and higher serum C-reactive protein (CRP) (p < .001) and OPG levels (p < .001) but lower creatinine (p = .013) and peritoneal Kt/V (p = .048) levels than those in the normal ABI group." (PMID 31950864, 2020). "There are limited data on the association between CRP and microvascular/macrovascular dysfunction in individuals without diabetes." (PMID 32665312, 2020). "Patients with certain co-morbidities such as diabetes and hypertension at baseline and/or laboratory parameters such as high concentration of CRP, LDH, and high concentration of D-dimer formed a higher risk subgroup with a higher likelihood of progression to ARDS." (PMID 33244300, 2020). "For prognostic models, these predictors include age, features derived from computed tomography scoring, lactate dehydrogenase, sex, C reactive protein, comorbidity (including hypertension, diabetes, cardiovascular disease, respiratory disease), and lymphocyte count." (PMID 32265220, 2020). "Patients with CVD events during follow-up were significantly older; had a higher comorbidity index, and higher plasma levels of C-reactive protein; they were more likely to have hypertension, diabetes, or a history of coronary heart disease, than those who did not develop CVD." (PMID 32161551, 2020). "In addition, they did not exclude people with cardiovascular disease and did not adjust for possible confounding factors, such as age, hypertension, diabetes, lipid profile, renal function, uric acid, CRP, and a habit of regular exercise." (PMID 32498283, 2020). "IL-6 on the other hand regulates the production of C-reactive protein (CRP), a systemic inflammatory biomarker that has been strongly associated with cardiovascular mortality, hypertension, coronary heart disease, stroke, and diabetes." (PMID 32566678, 2020). "Univariable analysis showed statistical significance in patients of older age (≥ 65 years, p = 0.042), diabetes mellitus (p = 0.001), a non-odontogenic cause of infection (p = 0.004), CRP > 10 mg/dL (p = 0.038), and multiple-space infection (p = 0.049)." (PMID 31815113, 2019). "Moreover, PAr was the strongest predictor of future stroke compared with each of the classical risk factors (diabetes, smoking, hypertension, glomerular filtration rate (GFR), and C-reactive protein (CRP))." (PMID 30845778, 2019). "Serum baseline levels of CRP are markedly higher in patients with diabetes or glucose intolerance." (PMID 31208420, 2019). "However, on top of HbA1c, age, and sex, MASP combined with CRP improved (pre)diabetes prediction significantly in terms of both IDI- and cfNRI-metrics." (PMID 30599058, 2019). "At day 30 after AMI, an increase in Galectin-3 plasma concentration in the median cubital vein of 1 unit, was independently associated with the 1.55-fold (p = 0.01) increased risk of LVR, six months after AMI, adjusted for age, leukocyte count, CRP and diabetes." (PMID 31511537, 2019). "However, serum concentrations of CRP were significantly reduced in subgroup analysis stratified by diabetes duration (− 0.23 mg/L, 95% CI, − 0.41 to − 0.05)." (PMID 31208420, 2019). "Subanalyses of the Diabetes Heart Study84 and FACTOR-6481 revealed that the factors with greater predictive power for ACS risk were the use of statins and LDL-c levels, followed by glomerular filtration rate, microalbuminuria, and C-reactive protein (CRP)." (PMID 31691761, 2019).
diabetes (continued). "Diabetes (adjusted odds ratio [aOR] 3.1, 95% CI 1.2−7.7), history of fever or fever at admission (aOR 3.9, 95% CI 1.4−11.1), higher serum C-reactive protein (aOR 1.08, 95% CI 1.05−1.11), and higher CSF lactate (aOR 3.5, 95% CI 2.3−5.4) were independent predictors of bacterial infection." (PMID 31002063, 2019). "Besides patients with diabetes, a cross-sectional analysis in patients with CKD showed that serum magnesium concentration also is inversely associated with C-reactive protein (CRP) concentrations, as a reflection of low-grade inflammation." (PMID 30813254, 2019). "Elevated CRP levels have also been found in other chronic diseases, such as diabetes." (PMID 31443226, 2019). "DPP4i could effectively reduce serum CRP concentrations, which might prevent exacerbation of cardiovascular events in diabetes progress." (PMID 31208420, 2019). "While MASP did not add statistically significant information on top of the GDRSadapted-variables, MASP combined with CRP improved the (pre)diabetes prediction on top of age, sex, and HbA1c with an IDI of 0.021 [0.005, 0.036] and a cfNRI of 0.270 [0.051, 0.481]." (PMID 30599058, 2019). "Multiple clinical studies have shown that most risk factors for coronary atherosclerosis were also risk factors for CMVD, such as smoking, being male, hyperhomocysteinemia, abnormal glucose tolerance, diabetes, hypersensitive CRP, hyperlipidemia, and other independent predictors of CMVD." (PMID 31008104, 2019). "This relationship was independent of traditional risk factors including diabetes, blood pressure, baseline renal function and CRP." (PMID 30791918, 2019). "In addition, that study showed a negative relation between RI and most of the traditional CVRFs such as arterial hypertension and diabetes, including the C-reactive protein as an overall marker of inflammation." (PMID 31882836, 2019). "Moreover, in multiple line regression analysis with UAE as the dependent variable, only duration of diabetes, HbA1c, hs-CRP, serum creatinine, and chemerin were independently associated with UAE." (PMID 31379940, 2019). "Further adjustment for CRP attenuated the association between GDF-15 quartiles and diabetes risk." (PMID 30350239, 2019). "Consequently, individuals in the highest ALT quartile had a higher hs-CRP and greater prevalence of glucose intolerance (prediabetes and diabetes) and hypertension." (PMID 30987010, 2019). "Our results revealed that C3 is associated with incidence of CKD hospitalizations in the general population, independent of traditional risk factors including diabetes, blood pressure, CRP and baseline renal function." (PMID 30791918, 2019). "Adjustmentfor potential risk factors with association to elevated hs‐cTnT (age, sex, BMI, hypertension, diabetes, hs‐CRP, smoking and physical activity), showed that FH‐HD and FH‐P‐HD remained significantly associated with elevated hs‐cTnT (OR=1.62, p=0.025 and OR=1.70, p=0.039, respectively)." (PMID 31175686, 2019). "In addition, patients in the high IL-6 group had a higher rate of diabetes mellitus and higher levels of serum C-reactive protein than those in the low IL-6 group (P = 0.0266 and 0.0073, respectively)." (PMID 30611204, 2019). "In addition, older age, more female patients, higher CRP, higher prevalence of diabetes mellitus, and lower Hb and BMI were found in the NTIS group and the renal dysfunction group than in the normal group after adjustment for age and sex (all P < 0.05)." (PMID 30832591, 2019). "HIV-positive status (adjusted regression coefficient -2.84, CI -5.00–-0.67, p = 0.011), diabetes (adjusted coefficient -2.85; CI, -5.58–-0.12; p = 0.041), and serum C-reactive protein and blood hemoglobin levels were independent predictors of serum albumin levels on multivariable linear regression." (PMID 31181128, 2019).